RN7SL165P (RNA, 7SL, cytoplasmic 165, pseudogene)
Gene: Miscellaneous RNA gene on chromosome 1 (26,814,822 to 26,815,112, forward strand). Ensembl gene ENSG00000241188.
Homologues: Orthologues: chimpanzee Metazoa_SRP (99% identical), macaque Metazoa_SRP (95% identical). Paralogues in human: RN7SL3 (82% identical), RN7SL1 (82% identical), RN7SL2 (81% identical), RN7SL566P (81% identical), RN7SL220P (80% identical), RN7SL797P (79% identical), RN7SL408P (79% identical), RN7SL630P (79% identical), RN7SL743P (79% identical), RN7SL230P (78% identical), RN7SL296P (78% identical), RN7SL498P (78% identical), and 704 more.